KCND1 (potassium voltage-gated channel subfamily D member 1)
Description:
A-type voltage-gated potassium channel that mediates transmembrane potassium transport in excitable membranes in the brain. Mediates A-type current I(SA) in suprachiasmatic nucleus (SCN) neurons. Exhibits a low-threshold A-type current with a hyperpolarized steady-state inactivation midpoint and the recovery process was steeply voltage-dependent, with recovery being markedly faster at more negative potentials. May regulates repetitive firing rates in the suprachiasmatic nucleus (SCN) neurons and circadian rhythms in neuronal excitability and behavior. Contributes to the regulation of the circadian rhythm of action potential firing in suprachiasmatic nucleus neurons, which regulates the circadian rhythm of locomotor activity. The regulatory subunit KCNIP1 modulates the kinetics of channel inactivation, increases the current amplitudes and accelerates recovery from inactivation, shifts activation in a depolarizing direction (By similarity). The regulatory subunit DPP10 decreases the voltage sensitivity of the inactivation channel gating.
Synonyms: Kv4.1
Tractability: Small molecule: an approved drug acts on it; it belongs to a druggable protein family. Antibody: its Gene Ontology location is reachable by antibodies, with high confidence; UniProt places it where antibodies can reach, with medium confidence; UniProt predicts a signal peptide or a membrane-spanning region.
Gene: Protein-coding gene on chromosome X (48,960,982 to 48,971,866, reverse strand). Ensembl gene ENSG00000102057.
Subcellular location: Cell membrane
Subcellular location (Human Protein Atlas): Nucleoplasm
Pathways (Reactome):
Muscle contraction: Phase 1 - inactivation of fast Na+ channels
Neuronal System: Voltage gated Potassium channels
Gene Ontology:
Molecular function: A-type (transient outward) potassium channel activity; monoatomic ion channel activity; voltage-gated potassium channel activity
Biological process: action potential; potassium ion transmembrane transport; monoatomic ion transport; potassium ion transport; protein homooligomerization; transmembrane transport
Cellular component: dendritic spine; neuronal cell body; plasma membrane; postsynaptic membrane; voltage-gated potassium channel complex; membrane
Homologues: Orthologues: chimpanzee KCND1 (100% identical), macaque KCND1 (99% identical), dog KCND1 (98% identical), pig KCND1 (97% identical), rabbit KCND1 (97% identical), guinea pig KCND1 (96% identical), rat Kcnd1 (95% identical), mouse Kcnd1 (95% identical). Paralogues in human: KCND3 (65% identical), KCND2 (65% identical), KCNB2 (30% identical), KCNA3 (28% identical), KCNA4 (27% identical), KCNA2 (27% identical), KCNC3 (27% identical), KCNC2 (27% identical), KCNA1 (27% identical), KCNA5 (27% identical), KCNC4 (26% identical), and 19 more.
Diseases named in the same sentence as KCND1 in open-access papers:
KCND1 is named in the same sentence as 18 diseases in open-access papers, as found by Europe PMC text mining. Sharing a sentence is not in itself a finding about the gene and the disease. The quoted sentences say what the papers report.
gastric cancer (3 papers, 2015 to 2023). A primary or metastatic malignant neoplasm involving the stomach. "Knockdown of KCND1 induced cell cycle G1‐S blockade and thus repressed the formation of gastric cancer cells." (PMID 37347147, 2023). "Knockdown of KCND1 inhibited the proliferation of gastric cancer cells." (PMID 37347147, 2023). "KCND1 has been reported to have oncogenic effect in gastric cancer." (PMID 34621669, 2021).
breast carcinoma (2 papers, 2015 to 2023). "Upregulation of KCND1 promoted tumorigenic effects in human breast epithelial cells, while repression of KCND1 expression suppressed the proliferative effects of breast cancer cells." (PMID 37347147, 2023).
neuroblastoma (2 papers, 2015 to 2023). Neuroblastoma (NB) is the most common solid, extracranial childhood tumor. "The overexpression of microtubule binding protein tau resulted in a decrease in the mRNA expression levels of KCND1, thereby suppressing the growth of murine neuroblastoma N2A cells." (PMID 37347147, 2023).
Childhood onset (1 paper, 2024). Onset of disease at the age of between 1 and 5 years. "However, in a single individual with childhood-onset focal epilepsy, a hemizygous KCND1 nonsense variant was identified as the prime candidate for a pathogenic variant." (PMID 38772379, 2024).
focal epilepsy (1 paper, 2024). A seizure caused by a localized disorder. "Also, a hemizygous nonsense variant of X-chromosomal KCND1 (MIM: 300281) has been suggested as a candidate pathogenic variant in a single individual with focal epilepsy, however, with no reference to Kv4.1 channel function." (PMID 38772379, 2024). "Although Kv4 channels play a crucial role in brain function, variants in KCND1 have not been associated with a human disease phenotype in OMIM, though a single individual with focal epilepsy has been reported as hemizygous for a truncating variant in this gene." (PMID 38772379, 2024).
cancer (2 papers, 2021 to 2023). A tumor composed of atypical neoplastic, often pleomorphic cells that invade other tissues. "The potassium voltage‐gated channel subfamily D (KCND, also known as Kv4) consists of three members, including KCND1 (Kv4.1), KCND2 (Kv4.2), and KCND3 (Kv4.3), which have been widely documented to be responsible for the initiation and advancement of cancers." (PMID 37347147, 2023). "In LGG, genes such as CDKL5, KCND1, and DDX3X that have a role in different cancers have differential expression and methylation." (PMID 34621669, 2021).
genetic disease (1 paper, 2024). "It will be interesting to see if KCND1 missense variants affecting the cytoplasmic gate are identified in the future and shown to be associated with a female-specific genetic disease." (PMID 38772379, 2024).
neurodevelopmental disorder (1 paper, 2024). A behavioral and cognitive disorder with onset during the developmental period that involves impaired or aberrant development of intellectual, motor, or social functions. "The KCND1 variants described herein are associated with a neurodevelopmental disorder characterized by a remarkable variability in the phenotypic expression and severity of the disease." (PMID 38772379, 2024). "From a clinical perspective, group 1 KCND1 variants are associated with a neurodevelopmental disorder variable in severity, with or without seizures." (PMID 38772379, 2024).
KCND1 also shares sentences with these, for which no sentence is quoted: tumor (2 papers); Anxiety (1); cognitive deficits (1); COVID-19 (1); epilepsy syndrome (1); haematological diseases (1); Infertility (1); lung adenocarcinoma (1); neurodegenerative disease (1); temporal lobe epilepsy (1).